CXCL1 (C-X-C motif chemokine ligand 1)
Diseases named in the same sentence as CXCL1 in open-access papers (continued):
Sharing a sentence is not in itself a finding about the gene and the disease.
cancer (continued). "The CXCLs (i.e., CXCL1, 2, 3, 5, 7 and 8)-CXCR2 signaling axis is involved in the recruitment of MDSCs in various types of cancers, including CRC." (PMID 38750114, 2024). "The angiogenic properties of CXCL1, EPC, and CXCR2+ cancer stem cells can compensate for blocking VEGF activity during anti-angiogenic therapy, which leads to resistance to treatment." (PMID 38673949, 2024). "The immunohistochemical analysis revealed significantly higher expression of CD44, MYC, IL17A, CXCL1, FCGR3A, SPP1, and IL1A in cancer tissues, while CXCL12 and CCL5 showed significantly higher expression in adjacent normal tissues." (PMID 39767563, 2024). "This suggests a positive correlation between the levels of CXCL1 expression and the progression of HCC cancer." (PMID 39132161, 2024). "Both MSCs and A431 cells secreted MIF, SERPIN1, IL-8, and CXCL1/GRO⍺, while CCL2 and IL-6 were only found in MSC cultures, and CCL5 and GM-CSF were only detected in cancer cell supernatants." (PMID 38674102, 2024). "This will result in immortal dysplastic epithelial cells exposed to upregulated SASP factors secreted by senescent fibroblast, such as IL-1, IL-6, IL-8 and GRO-α/CXCL-1, which will increase ROS production, generating DSB, favoring cancer development." (PMID 37904749, 2023). "These signature included EGFR, COX2, and the matrix metalloproteinases 1 (MMP1), CXCL1 and IDI1 which were highly expressed in the Triple Negative subtype and HER2-positive cancers." (PMID 36761968, 2023). "Transcriptome analysis revealed that CHRM3 knockdown significantly reduced an array of classic factors involved in cancer invasive growth, including MMP1/MMP3/MMP10/MMP12 and CXCL1/CXCL5/CXCL8." (PMID 37744266, 2023). "Taking into consideration the cancer development process, the following histaminergic genes stood out: GNA15, HRH1-HRH4, MAOA, WASF2, along with inflammation-related genes: AEBP1, CXCL1, CXCL2, CXCL3, CXCL8, SPHK1, and TNFAIP6." (PMID 36902343, 2023). "Transcriptome analysis revealed that CHRM3 knockdown significantly reduced an array of classic factors in cancer invasive growth including MMP1/MMP3/MMP10/MMP12 and CXCL1/CXCL5/CXCL8." (PMID 37744266, 2023). "Starting from alveolar cells, the cells transformed into pathological alveolar cells, CXCL1, LAMC2, CDKN2A, proliferating, and SOX2 cancer cells as they progressed in pseudotime." (PMID 36973297, 2023). "The study explores how chemotherapy upregulates CXCL1 and CXCL5, in cancer cells in ling metastases, resulting in neutrophil recruitment." (PMID 38062888, 2023). "Many cancer cells exhibit induction or increased expression of multiple ligands for both CXCR1 (CXCL1-3, 5–8) and CXCR2 (CXCL1-3, 5 and 7)." (PMID 37270599, 2023). "Correlation analysis also shows that the following histaminergic transcripts: GNA15, HRH2, MAOA, WASF2, and those related to inflammation: AEBP1, CXCL1, 2, 3, and 8, SPHK1, and TNFAIP6 play an important role in cancer tissue." (PMID 36902343, 2023). "Neutrophils can also accumulate in the metastatic niche, where the expression of G-CSF, CXCL1, and CXCL2 by cancer cells and stromal cells promote their recruitment." (PMID 37444436, 2023). "We classified the cancer cells into the five cancer subtypes as CDKN2A, SOX2, CXCL1, LAMC2, and proliferating cancer based on the top markers that are highly expressed in each cluster." (PMID 36973297, 2023). "Endothelial cell-generated TNF-α then triggers CXCL1/2 expression by cancer cells, which subsequently recruits CD11b+Gr1+ myeloid-derived suppressor cells that express CXCR2 (the receptor for CXCL1/2)." (PMID 36241629, 2022). "Out of the detected hub genes, six (CCL20, CXCL1, CXCL3, CXCL8, CXCL11, and MMP1) were among over-expressed vDEGs which have been corroborated by the GEPIA in both COAD and READ cancer types." (PMID 35333898, 2022). "Among those downregulated, CXCL1, CCL2, CXCL8, CTGF, LIF, and IL-6 are known to be involved in fibrosis or cancer stroma." (PMID 36289649, 2022).
cancer (continued). "During cancer development, secreted factors such as VEGF, IL-8, IL-6, and the chemokine (C-X-C motif) ligand 1 (CXCL1) promote tumor progression by stimulating angiogenesis." (PMID 35745875, 2022). "Further supporting the functional link between HB-EGF and CXCL1, we found a positive correlation between the expression of HB-EGF and CXCL1 in several types of human cancer." (PMID 35998057, 2022). "Upregulation of CXCL1 and CXCL3 has been found to potentiate infiltration of immunosuppressive neutrophils, favoring cancer cells escaping from immune surveillance." (PMID 36612163, 2022). "Collectively, these results demonstrate that CXCL1/2 and their receptor CXCR2 play key roles in M2 TAMs-induce SOR resistance and cancer stemness in HCC cells." (PMID 36411463, 2022). "Patients with both CXCL1- and CXCR2-positive cancer (n = 28) had significantly better prognoses than those with CXCL1- and/or CXCR2-negative cancer (n = 132) (p = 0.042)." (PMID 35377900, 2022). "A curcumin-dependent downregulation of the chemokines C-X-C motif chemokine ligand (CXCL)-1 and CXCL-2 in cancer cells was observed, which was influenced by NF-κB, a transcription factor associated with inflammation and cancer progression." (PMID 35631330, 2022). "Cancer cell proliferation is stimulated by MSC-derived chemokines CXCL1/2 and CXCL12/SDF-1 that activate signaling pathways dependent on respective CXCR2 and CXCR4 receptors expressed by cancer cells." (PMID 35269887, 2022). "Under chemotherapy, the CXCL1/2–S100A8/9 survival signaling axis is hyper-activated, which decreases the sensitivity of cancer cells to therapeutic medicine." (PMID 36612163, 2022). "Promotion of lung metastasis also is induced by secretion of CXCL1 and VCAM-1 expression and this regulates trans-endothelial migration of cancer cells." (PMID 33466892, 2021). "CTX also inhibits chemokines that bind to CXCR1 and CXCR2 receptors such as CXCL5, CXCL1/2/3, CXCL1a, CXCL6, and CXCL8 (IL-8) that are involved in cancer angiogenesis and metastasis." (PMID 34822613, 2021). "The smallest cluster (labeled CXC-1) was enriched for cells expressing CXC motif ligands such as CXCL1, CXCL2, and CXCL8, which are thought to stimulate cancer cell proliferation and migration." (PMID 34611171, 2021). "But this study identified the significant (p<0.05) up-regulation of CXCL1 mRNA in COAD patients of different races, cancer stages, genders, age groups, and body weights." (PMID 34473751, 2021). "Taken together, CXCL1/CXCR2 is involved in the development of neuropathic, inflammatory, and cancer pain." (PMID 33531894, 2021). "The CXCL1 is often cosecreted with inflammatory cytokines such as IL-1, IL-6, and TNF-α by infiltrating macrophage or cancer cells." (PMID 34803728, 2021). "Cancer cells promote neutrophil ET formation and are closely related to the inflammatory cytokines ICAM-1, VCAM-1, E-selectin, IL1, IL6, CXCL1, and C3a receptors." (PMID 34084158, 2021). "In addition, CXCL1 could modulate inflammation and cancer progression." (PMID 33867350, 2021). "Our data indicate that muscle-derived CXCL1, IL10 and CCL4 are part of the mechanistic link between exercise and the induction of apoptosis in cancer cells." (PMID 34359731, 2021). "Protein–protein interaction analysis of common DEGs in L. brandtii showed that the most significant core genes were CXCL1, MMP9, JUN, ANXA2, and F5, which regulate immune response and cancer progression." (PMID 32256671, 2020). "While CCL14 and XCL1 have shown only good prognostic value, other chemokines such as CCL5, CCL20/CCR6, CCR7, CXCL1, CXCL8, and CXCL12/CXCR4 have consistently played the role of poor prognostic markers in different kinds of cancer." (PMID 31991604, 2020).
cancer (continued). "Interleukin-6 (IL-6), IL-8, transforming growth factor β (TGF-β), CXCL1, or VEGF are examples of soluble factors with pleiotropic effects that can foster cancer growth and spread." (PMID 33220234, 2020). "A six-biomarker model (HE4, CA125, CXCL1, ITGAV, CEACAM1, IL-10RB and age) was the best model for discrimination between benign tumors and borderline tumors + cancer, with AUC 0.868 and sensitivity 0.86 / specificity 0.82 at best point cut-off (p = 0.016)." (PMID 33075095, 2020). "C-X-C motif chemokine ligand 1 (CXCL1) is a member of the CXC subfamily of chemokines and an oncogenic factor in many cancers." (PMID 32326946, 2020). "Then MSCs are recruited into contact with OS cells, trans-differentiate into cancer-fibroblasts, and secret more MCP-1(CCL2), GRO-α (CXCL1), TGF-β, IL-6, and IL-8 in the microenvironment." (PMID 32977425, 2020). "With regard to up-regulated DEGs enriched in immune response, it is now well-established that FGR, CXCL1, NLRC4 and S100A9 influence the pathogenesis of cancer by modulating immune responses and promoting progression, aggressiveness and cell survival 32-35." (PMID 32922167, 2020). "Recently, studies on CXCL1, CXCL5, and CXCL7 mainly focus on the biomarker and pathogenesis of various malignant tumors, but a few about CNS IIDDs existed." (PMID 32515897, 2020). "For example, it has been reported that CXCL1, a functional homologue of CXCL8 in mice, recruits CD11b+ Gr1+ myeloid cells in vivo, which contributes to the cancer progression." (PMID 31147602, 2019). "Another interesting observation was that the unmodified alginate samples contained CXCL1, CXCL2, CXCL12, which are powerful neutrophil chemoattractants that are involved in many immune responses including wound healing, cancer metastasis, and angiogenesis." (PMID 31748525, 2019). "Our results point to a new paracrine activation loop between PCa cells, stromal myofibroblasts, and neutrophils involving CXCL1 and LCN2, which are shown to confer a more invasive phenotype to cancer cells by activating Src family kinases and EMT." (PMID 31500632, 2019). "For example, peri-tumor tissue-sourced fibroblasts secrete various cytokines, including IL-6, CXCL1, CCL2, SCGF-β, CXCL8 and HGF, to recruit cancer stem cells, maintain cancer stemness and promote intrahepatic metastasis of HCC." (PMID 30999932, 2019). "Hypoxia promoted cancer cell production of more macrophage chemokines, and among all increased chemokines (CCL2, CCL5, CCL8, CCL19, CCL21, and CXCL1), CCL8 was the most increased according to qRT-PCR detection." (PMID 31263103, 2019). "CAFs produce autocrine and paracrine cytokines, chemokines and growth factors like CXCL1, CCL5, HB-EGF and TGF-α, subsequently promoting cancer cell invasiveness through upregulation of matrix metalloproteinases (MMPs) and induction of EMT." (PMID 31888563, 2019). "Proinflammatory chemokines such as CXCL1, 2, 3, 5, 6 and 8 interact with the CXCR2 receptor and can mediate angiogenesis during cancer development." (PMID 30034618, 2018). "Therefore, CXCL1 may be a biomarker for cancer prognosis and a therapeutic target for this disease." (PMID 30158589, 2018). "Several of these pro-inflammatory chemokines such as CXCL1, CXCL8 and CXCL12 drive cancer progression by facilitating cell growth, survival and migration and inducing angiogenesis." (PMID 29719625, 2018). "We postulate that CXCL1 and 8 potentiate EGFR transactivation in TNBC cells to enhance the cancer aggressiveness and chemoresistance." (PMID 30034618, 2018). "Therefore, we also examined whether the expressions of Cxcl1-3,5 were affected by cancer cachexia." (PMID 30300394, 2018). "There are reports shown that fibroblasts involve in the cross-talk of cancer cells and fibroblasts by secreting CCL2, CCL5, CXCL1, CXCL6, CXCL12, IL6, CXCL16 and others." (PMID 28465475, 2017).
cancer (continued). "On the other hand, the neutrophil chemotactic chemokines, CXCL-1 and CXCL-8, have been shown to be pro-tumorigenic and pro-angiogenic by their ability to recruit pro-tumorigenic neutrophils into cancer tissue." (PMID 29387062, 2017). "In line with their high potential for functional impact, CXCL1, CXCL5, CCL2, and IL-8 were also significantly induced by TRAIL in different cancer cell lines, as determined by ELISA, antibody-based cytokine array, and qPCR." (PMID 28212753, 2017). "For example, over-expression of CXCL1 and CXCL2 favors cancer cell survival in metastatic sites through the induction of S100A8 and S100A9 secretion from CD11b+Gr1+cells." (PMID 28429725, 2017). "Regardless of clinicopathological characteristics, significant expression differences were observed, including 10 upregulated genes (CCL4/18, CXCL1/10/11, IFNγ, IL2/6/12A, VEGFA) and 1 downregulated gene (HLA-A) in lymphocytes from malignant ascites." (PMID 28620375, 2017). "In our study, expression of proinflammatory chemokines IL-8, CXCL1, CXCL2, and CCL3 was upregulated in the early stages of cancer progression." (PMID 27143385, 2016). "Combined, these results indicate that both mouse and human ASCs are chemoattracted to CXCL1, as well as to CXCL8 secreted by cancer cells." (PMID 27241286, 2016). "From these results, we established CXCR4, CXCL1 and HMGCS1, the intersecting genes of the datasets with high connectivity and p-value of < 0.05, as significant genes in the identification of cancer stem cells." (PMID 26870956, 2016). "Elevated levels of CXCL1 and CXCR2 positively correlate with the poorer prognosis of cancer patients." (PMID 27446967, 2016). "Mediators secreted by these cells that directly or indirectly promote cancer cell growth include cytokines, chemokines, and growth factors, such as VEGF-A, CSFs, IL-1, IL-6, IL-8, or CXCL1." (PMID 26343581, 2015). "Although chemotherapeutic agents kill cancer cells, they induce TNF-α production by endothelial and stromal cells, which upregulates CXCL1 and CXCL2 in cancer cells, amplifying the CXCL1/2-S100A8/9 loop and affecting chemoresistance." (PMID 25165728, 2014). "Cancer cells overexpressing CXCL1 and CXCL2 attract CD11b(+)Gr1(+) myeloid cells into the tumor and produce chemokines including S100A8/9 that enhance cancer cell survival." (PMID 25562519, 2013). "It has been shown that matrix metalloproteinase-1 (MMP-1) causes activation of PAR1 leading to expression of the pro-angiogenic secreted chemokines CXCL8 (IL-8), CXCL1 (GRO-α), and CCL2 (MCP-1) by the cancer cells." (PMID 24384839, 2013). "Despite the increasing number of studies indicating a role for CXCL1, CXCL5 and CXCL6 in different cancer types and processes, their relevance with view to the development of CRC is still rather limited." (PMID 18578857, 2008). "Summarizing, our findings uncover a paracrine signaling involving CXCL1 and MLK4-NF-κB-MMPs axis, which mediates the interactions between TAMs and TNBC cells, enhancing proliferation, mesenchymal transition, ECM remodeling and cancer invasion." (PMID 41922320, 2026). "Additionally, the interactions between chemokines, including CXCL1, CXCL8, and CCL2, and ACKR1, expressed by endothelial cells, were notably greater in MHC-II+ cancer cells than in MHC-II− cancer cells." (PMID 41281745, 2025). "Cancer cells modulate the expression and secretion of several anti-proliferative molecules on DBMSCs, including, CD40LG, CXCL9, IL9R, IL-15, TNFSF13B, IL-9, IL-17, and CXCL1." (PMID 39768220, 2024). "Several studies have evidently shown that chemokines (such as CCL2, CCL5, CXCL1, and CX3CL1) are involved in neuronal sensitization or microglia activation in the spinal cord, and some of these chemokines contribute to the development of cancer pain." (PMID 39641645, 2024). "The production of the chemokine CXCL1 of cancer cells arrests T cell infiltration, thus generating a non-T- cell-inflamed TME that affects immunotherapy sensitivity." (PMID 38817612, 2024).
cancer (continued). "In the present study, although the extent of senescence elicited by DNA‐damaging agents and CDK4/6i was similar, CDK4/6i‐induced senescent cancer cells showed significantly lower expression of well‐known pro‐inflammatory SASP such as IL‐6, CXCL1, CXCL8, and TGF‐β." (PMID 37854019, 2024). "In additional experiments, where we compared healthy mice to 4PYR-treated animals, we found that 4PYR has contributed to significantly increased expression of cytokines related to inflammation and cancer progression, such as CCL3, CXCL1, CCL5 or IL-1A and IL-1B." (PMID 39795893, 2024). "Previously, we found that chemotherapy topoisomerase inhibitors could promote the ROS-elevated expression and secretion of CXCL1, activating JAK2-STAT1 signaling pathway and inactivating PTP1B, thereby promoting the migration and invasion of cancer cells." (PMID 39390002, 2024). "Although its relevance across various cancers has been well-researched, there is no comprehensive overview summarizing the entirety of CXCL1’s significance in cancer processes." (PMID 38673949, 2024). "At the same time, CXCL1 is not necessary for sphere-forming, stemness, or self-renewal of cancer stem cells in thyroid tumors." (PMID 38673949, 2024). "Besides its role in cancer, CXCL8, along with CXCL1, 2, and 5 are noted for their autocrine and/or paracrine effects in reinforcing senescence." (PMID 38385965, 2024). "Approximately 70% of cell lines derived from this cancer show CXCL1 expression, compared to a lack of CXCL1 expression in normal melanocytes." (PMID 38673949, 2024). "These physiological and non-cancer disease-related properties reflect the role of CXCL1 in cancer processes." (PMID 37108425, 2023). "Blood CXCL1 level is also elevated in hepatitis B-related HCC, and for this reason may be used as a biomarker of this cancer." (PMID 37408240, 2023). "However, it has also been reported that CXCL1 and CXCL2 have bidirectional roles in cancer progression." (PMID 37310469, 2023). "Cultivating three different types of breast cancer cell lines by CM derived from young and senescent HPMCs, it was observed that the secretory levels of pro-angiogenic agents, including CXCL1, CXCL8, the hepatocyte growth factor (HGF), and the VEGF, were significantly increased in cancer cells." (PMID 37046588, 2023). "Also, RNAseq of cancer cells recovered from untreated tumors revealed elevated levels of CXCL9 and 10 in EA2 tumors, and higher levels of CXCL1 and 2 in EA1 tumors." (PMID 36739466, 2023). "In biopsies lacking CALB1 expression, cancer cells not only transcribed CXCL1, CXCL2, CXCL8, and other immune mediators; they were also the predominant source." (PMID 37192000, 2023). "The −984 bp to −301 bp region, upstream of the transcription start site of the CXCL1 gene, contains a binding site for Snail, a transcription factor crucial for epithelial–mesenchymal transition (EMT), a process important in cancer cell migration, invasion and metastasis." (PMID 35054978, 2022). "We observed that among the members of the family of CXCR2 ligands, CXCL1, one of the ligands for CXCR2, produced by cancer cells might play an important role among CXCR2 ligands family in gastric cancer." (PMID 35377900, 2022). "In addition, Il18, Tnf, Ptgs2, Cd47, Cxcl1, and Csf1 were more highly expressed in STOSE tumors, including in the cancer cells, supporting the influence of TAMs in these tumors." (PMID 36311166, 2022). "We performed ELISA to determine whether macrophages affect CXCL1 and CXCL2 secretion in cancer cells." (PMID 36552865, 2022). "ELR-positive chemokines, including CXCL1 and CXCL5, induce cancer cell migration and invasion; hence, we tested whether the secretion of CXCL1 and CXCL5 was downregulated in our cancer cell-macrophage cocultures, using the same experimental setup as before." (PMID 35998057, 2022).